VDR (vitamin D receptor)
Diseases named in the same sentence as VDR in open-access papers (continued):
Sharing a sentence is not in itself a finding about the gene and the disease.
rickets (continued). "A hereditary vitamin-D-resistant rickets with facial dysmorphism has been reported, but the involvement of VDR signaling during early stages of craniofacial development remains to be elucidated." (PMID 31234506, 2019). "This is the first reported case of a patient with a mutation in the 360th residue of the human VDR, located on helix 9 of the LBD, which was associated with rickets and alopecia." (PMID 28698609, 2017). "VDDR2B (MIM 600785) is an unusual form of rickets due to abnormal expression of a hormone response element-binding protein that interferes with normal function of VDR." (PMID 29280738, 2017). "Nevertheless, the clinical features of severe rickets unresponsive to high-dose vitamin D therapy, combined with alopecia, indicated a severe defect in the function of the VDR." (PMID 28698609, 2017). "We consider that although the mutant VDR in this case is inactive, high calcium diet induced passive calcium transport at the intestine and improved her rickets." (PMID 26153892, 2015). "Both humans and mouse models that lack functional VDR display severe hypocalcemia, hypophosphatemia, rickets and osteomalacia highlighting a physiological significance of VDR in maintaining skeletal integrity." (PMID 22028889, 2011). "Genetic deficiencies in 1,25(OH)2D3 caused by loss of a functional 1α(OH)ase enzyme or vitamin D receptor (VDR) result in hypocalcemia, hyperparathyroidism, hypophosphatemia, rickets, and osteomalacia." (PMID 21966280, 2011). "Most patients with VDR-dependent rickets condition have a range of signs and symptoms, including alopecia, hypocalcemia, hypophosphatemia, impaired bone formation, growth retardation, female infertility, uterine hypoplasia, impaired folliculogenesis, and hyperparathyroidism." (PMID 38318147, 2024). "Although rickets and osteomalacia were prevented in vitamin D receptor (VDR) knockout mice fed with a rescue diet that contained high levels of calcium and phosphorus, not all bone changes were rescued, indicating the importance of a direct role for 1α,25-OH2D3 in bone metabolism." (PMID 36771187, 2023). "In addition, intestine-specific transgenic expression of VDR in VDR null mice normalized calcium absorption, serum calcium, and prevented the development of rickets." (PMID 35779631, 2022). "A total lack of VDR or CYP27B1 causes rickets but this is mainly due to its effect on intestinal calcium absorption as shown by the correction of bone and growth plate structure by a rescue diet of high calcium and lactose." (PMID 35334824, 2022). "In summary, although genomic pathways activated by VDR still remain the major targets for vitamin D, with clear clinical implications (e.g., rickets), the existence of alternative pathways explains fast responses to vitamin D, and its direct impact on mitochondria and other intracellular processes." (PMID 36501134, 2022). "A systems-level appreciation for vitamin D signaling has existed for several centuries, given that a description of rickets was first described in the 17th century; rickets arises from impaired bone mineralization due to insufficient signaling via the vitamin D receptor (NR1I1/VDR)." (PMID 36558356, 2022). "Diabetic population with hypovitaminosis D may suppress the signals of vitamin D receptor and result in the development of foam cells, subsequently increasing the cholesterol level in blood, which contribute to atherogenesis leading to CVDs." (PMID 34017921, 2021). "A high-Ca diet can cure rickets/osteomalacia in global VDR-KO mice." (PMID 32987399, 2020). "An unusual form of rickets, vitamin D-dependent rickets type 2B, was reported to have abnormal expression of a hormone response element-binding protein C1/C2 that interferes with the normal function of the vitamin D receptor." (PMID 26422470, 2015). "In conclusion, the VDR polymorphism itself does not play a major role in high prevalence of rickets in Mongolia, nor in reduced speed of sound of tibial cortical bone in childhood." (PMID 17202743, 2007).
rickets (continued). "Additionally, it may modulate pain signaling through the VDR expressed in the central nervous system, potentially linking hypovitaminosis D with exacerbation of fibromyalgia symptoms." (PMID 41156485, 2025). "The medical importance of NRs has been appreciated at least since rickets was first described in the 17th century by Daniel Whistler; rickets arises from a lack of bone mineralization due to insufficient signaling via the NR, the vitamin D receptor (NR1I1/VDR)." (PMID 35626007, 2022). "Mutations in the VDR gene can hinder the effect of vitamin D on calcium regulation and may result in diseases such as vitamin D-resistant rickets type 2a (VDDR2A), a condition described with hypocalcemia, hyperparathyroidism and rickets." (PMID 34444650, 2021). "However, it is not likely that severe function perturbing mutations of the vitamin D receptor in human are associated with Gardner's syndrome as rickets has not been reported in FAP patients." (PMID 27768599, 2016). "Vitamin D-dependent rickets type 2B with normal VDR (VDDR2B; MIM 600785) is a rare form of rickets due to an abnormal protein (HNRNPC) that interferes with the function of the VDR gene." (PMID 35565821, 2022). "Reduced apoptosis of hypertrophic chondrocytes was also reported in vitamin D receptor (VDR) knockout mice, and hypophosphatemia has been suggested to be a common etiologic factor among all types of rickets." (PMID 30972027, 2019). "Deletion or inactivation of the vitamin D receptor (VDR) in mice and in humans leads to rickets, a phenotype completely reversible in both organisms by treatment with calcium." (PMID 24800251, 2014). "The absence of the vitamin D receptor (VDR) in mice (after weaning) leads to a severe phenotype characterized by hypocalcemia, rickets, alopecia, growth retardation, and reproductive disorders, indicating the essential role of the vitamin D-VDR axis." (PMID 41301826, 2025). "Similar to our study, other studies have not demonstrated significant changes in sperm parameters with deficient Vitamin D. In particular, one case series described four fertile males with 1,25-dihyroxyvitamin D-resistant rickets due to a non-functioning VDR." (PMID 36096748, 2022). "Global VDR-KO mice do not exhibit abnormalities before weaning (3 weeks of age) and develop rickets or osteomalacia after weaning." (PMID 32987399, 2020). "In conclusion, present findings suggested that low levels of serum 25(OH)D and VDR expression are associated with a higher kidney volume in ADPKD patients, but hypovitaminosis D does not represent an independent risk factor for increasing kidney volume." (PMID 31179282, 2019). "Paradoxically, FF (shorter VDR) was correlated with rickets unlike ff (longer VDR) in Turks and Egyptians." (PMID 22536488, 2012). "Our results did not indicate significant differences in VDR genotype distribution among children with and without a history of rickets." (PMID 17202743, 2007). "Distribution of vitamin D receptor (VDR) genotypes among children with a history of rickets (cases) and those with no history of rickets (controls) in Ulaanbaatar." (PMID 17202743, 2007). "Calcitriol is a non-selective vitamin D receptor activator, that could be used to treat renal dystrophy, hypoparathyroidism, and vitamin D-dependent and -resistant rickets in patients with chronic renal failure." (PMID 37529325, 2023). "Thus, despite the limitations, different genotypes of BsmI SNP of the VDR gene modulated the expression of the VDR, CYP24A1, and SOD2 genes even though they did not alter the circulating levels of vitamin D in individuals with hypovitaminosis D." (PMID 37630755, 2023). "Finally, the negative correlation between both 25(OH)D levels and VDR expression with htTKV disclosed in the present study, suggested a potential contributionof hypovitaminosis D to kidney enlargement in ADPKD." (PMID 31179282, 2019).
rickets (continued). "Mice lacking the vitamin D receptor (VDR) develop hypocalcemia, severe hyperparathyroidism, elevated plasma levels of alkaline phosphatase, and the typical features of rickets." (PMID 28912809, 2017). "However, we also found variants in genes associated with primary hyperparathyroidism (GCM2), renal hypophosphatemia with or without rickets (SLC34A1, SLC34A3, SLC9A3R1, VDR, and CYP27B1), DiGeorge syndrome (TBX1 and NEBL), and hypophosphatasia (ALPL)." (PMID 38586466, 2024).
autoimmune disease (95 papers, 2007 to 2026). A disorder resulting from loss of function or tissue destruction of an organ or multiple organs, arising from humoral or cellular immune responses of the individual to their own tissue constituents. "It should be noted that the association between VDR polymorphisms and autoimmune diseases definitely differs across ethnic populations." (PMID 41226614, 2025). "Its deficiency, along with genetic variations in the vitamin D receptor (VDR), has been linked to autoimmune diseases." (PMID 40395263, 2025). "Four single nucleotide polymorphisms (SNPs) of the VDR gene, ApaI, BsmI, TaqI, and FokI, in particular, have been associated with autoimmune disorders." (PMID 37508347, 2023). "These will help to support the clinical and translational nutrigenetic interventions with vitamin D supplementation according to the VDR genetic variants in subsequent studies conducted on patients with autoimmune diseases." (PMID 36360253, 2022). "An increased utilization of vitamin D during active inflammation, possibly operated by VDR polymorphisms, was theorized in patients with autoimmune diseases." (PMID 35458099, 2022). "In recent years, numerous studies have investigated the association of VDR gene polymorphisms with the risk of developing autoimmune diseases throughout different populations." (PMID 34977255, 2021). "VDR gene polymorphisms have been implicated in several autoimmune disorders, including systemic lupus erythematosus, rheumatoid arthritis and psoriasis." (PMID 34208603, 2021). "Alterations in calcitriol levels and polymorphisms of the VDR gene have been shown to be associated with several malignant and autoimmune diseases, including psoriasis vulgaris." (PMID 33419149, 2021). "Critically, several VDR SNPs have been revealed that are increasingly associated with multiple autoimmune diseases, either individually or as haplotypes." (PMID 33897704, 2021). "VDR SNPs (single nucleotide polymorphisms) have been also described as associated to autoimmune diseases, such as systemic lupus erythematosus (SLE), rheumatoid arthritis (RA), or multiple sclerosis (MS)." (PMID 34977255, 2021). "Vitamin D status and VDR polymorphisms appear to correlate with the incidence and severity of autoimmune diseases." (PMID 32373353, 2020). "The functional consequence of these VDR polymorphisms is important in determining the potential effect on inflammatory mediators in autoimmune diseases." (PMID 32727130, 2020). "VDR polymorphisms have been implicated in susceptibility to a variety of autoimmune diseases and cancers in a genome-wide association study and meta-analysis." (PMID 31565578, 2019). "Previously, we reported how the human Vitamin-D receptor (VDR) and its ligand, 1,25-dihydroxyvitamin-D (1,25-D), are associated with many chronic inflammatory and autoimmune diseases." (PMID 27412293, 2017). "In summary, autoimmune diseases are correlated with 25(OH)D3 serum levels, vitamin D intake, UV exposure, and VDR polymorphisms." (PMID 28163705, 2016). "In the context of autoimmune diseases, this is illustrated by correlations of vitamin D status and genetic polymorphisms in the vitamin D receptor with the incidence and severity of the disease." (PMID 28163705, 2016). "The Central European literature about the possible association of VDR gene polymorphisms and autoimmune diseases is very limited." (PMID 25649962, 2015). "The BsmI and/or FokI VDR polymorphisms have also been recognized as risk factors of some other autoimmune diseases, including RA, Behçet’s, Graves’ and Addison’s diseases, psoriasis, MS, T1D, and others." (PMID 23065277, 2013). "It is known that the deficiency of active vitamin D and polymorphism of the vitamin D receptor (VDR) are associated with increased incidence of several autoimmune diseases." (PMID 23853726, 2013). "In concordance, VDR expression and activity are associated with immunity against certain infections and with the prevalence of some autoimmune diseases." (PMID 23785369, 2013).
autoimmune disease (continued). "We assessed overlap between VDR ChIP-seq peaks and genomic regions encompassing the area 100 kb around SNPs significantly associated with autoimmune disease in genome wide association studies." (PMID 23849224, 2013). "Even so, VDR-KO mice appear to have a more vigorous immune response as seen by their increased risk of development of autoimmune diseases, and the enhanced response of VDR-KO T cells in mixed lymphocyte reactions." (PMID 23785369, 2013). "ChIP-seq experiments using immune cell lines have shown that vitamin D receptor (VDR) binding sites are enriched near regions of the genome associated with autoimmune diseases." (PMID 23849224, 2013). "VDR gene is located on the chromosome 12q12 and its polymorphisms have been related to different autoimmune disorders such as type I diabetes or Addison’s disease." (PMID 22654557, 2011). "VDR gene is another HT predisposing gene, common for other organ-specific autoimmune diseases such as type I diabetes or Addison’s disease." (PMID 22654557, 2011). "VDR polymorphisms may alter VDR function and signaling, thereby affecting the immunomodulatory role of vitamin D in the context of autoimmune diseases." (PMID 41516427, 2026). "The role of the VDR is further supported by studies on single-nucleotide polymorphisms (SNPs), which show that certain SNPs in VDR genes (e.g., ApaI, BglI, and TaqI), associated with reduced efficacy of vitamin D supplementation, have been linked to autoimmune diseases, including IBD." (PMID 40647273, 2025). "VDR SNPs were found to be associated with the pathogenesis of most of the autoimmune diseases reviewed here, and some risk and/or protective SNP alleles and genotypes appear to be shared by different autoimmune disorders." (PMID 37508347, 2023). "Our findings suggest that the association between 25(OH)D and T1DM may be modified by VDR variants, possibly influencing the development of this autoimmune disease." (PMID 35267984, 2022). "VDR polymorphisms have been associated with multiple autoimmune disorders, including psoriasis." (PMID 34208603, 2021). "Authors20 have hypothesised that, in individuals with low vitamin D levels and/or other predisposing genetic factors, the FF short-VDR genotype may represent an additional trigger for development of autoimmune diseases." (PMID 33067526, 2020). "Although their functional significances remain unknown, LD in combination with one or more functional polymorphisms elsewhere in the VDR gene are believed to explain observed associations between the VDR gene and autoimmune diseases." (PMID 28066436, 2016). "Given the potential role VDRs have on immune responses and intestinal homeostasis, VDR genetic variants have also been studied as potential factor of autoimmune diseases since they may influence VDR activity." (PMID 28066436, 2016). "The latest findings suggest that allelic variations of VDR gene may partially represent a genetic component associated with incidence, clinical symptoms, or severity of autoimmune diseases or to the susceptibility of them." (PMID 25649962, 2015). "However, little information on infection, inflammation and autoimmune disease was reported in these patients, suggesting that the underlying VDR-independent compensatory mechanism remains to be determined." (PMID 26422470, 2015). "Deficiency of both vitamin D and VDR causes development of certain autoimmune diseases." (PMID 24455278, 2013). "As vitamin D (and the vitamin D receptor) has been found to be reduced in patients with autoimmune disease, and reduced vitamin D is noted in higher latitudes which have higher rates of autoimmune disease, a role for vitamin D deficiency in autoimmunity is suspected." (PMID 22693505, 2012). "Association of MHC class-II alleles with an autoimmune disease could be due to its antigen presenting function and VDR may have a role in regulation of autoimmune responses through VDR −1,25 (OH)2D3 complex." (PMID 19956544, 2009).